INS (insulin)
Diseases named in the same sentence as INS in open-access papers (continued):
Sharing a sentence is not in itself a finding about the gene and the disease.
Hyperglycemia (continued). "Accordingly, we conducted a prospective, observational, exploratory study to assess the effect of insulin therapy on early levels of c-peptide as a surrogate marker of beta-cell function during moderate permissive hyperglycemia in patients with T2DM admitted to ICU." (PMID 28497374, 2017). "In a complementary analysis of the CREATE‐ECLA study that showed a lack of benefit from GIK infusion, Chaudhuri et al16 suggested that ≈18% in mortality could be reduced if GIK‐induced hyperglycemia was avoided by insulin therapy." (PMID 29138181, 2017). "Furthermore, administration of a centrally active galanin analog with high affinity for GalR1 has been recently shown to reduce insulin secretion and promote hyperglycemia, providing a further understanding on the role of GalR1 in vivo." (PMID 28729853, 2017). "Ghrelin also plays a role in glucose homeostasis: it may induce hyperglycaemia and diminish insulin secretion by binding to the GHS-R on β-cells." (PMID 28493909, 2017). "A defect in insulin processing was confirmed by elevated immunostaining for proinsulin concomitantly with decreased insulin staining in β-cells of βraKO mice before the onset of hyperglycaemia (30 days of age)." (PMID 28699639, 2017). "GLP-1’s function as an incretin, acting to stimulate insulin secretion and inhibit glucagon secretion, has been exploited pharmacologically for the purposes of limiting post-prandial hyperglycemia in T2DM, and GLP-1 receptor agonists have been demonstrated to promote weight loss." (PMID 27465935, 2017). "Increased insulin secretion after treatment with F. carica positively altered the deranged carbohydrate metabolism in the diabetic rats by decreasing gluconeogenesis and increasing glycolysis, ultimately decreasing hyperglycemia." (PMID 28193094, 2017). "Furthermore, hyperglycaemia requiring insulin treatment and drug cost increased with corticosteroid use." (PMID 29284447, 2017). "While acute hyperglycemia has been shown to mitigate the beneficial effects of ischemic preconditioning, its effect on insulin-induced preconditioning remains unclear." (PMID 28376800, 2017). "Calculation of relative hyperglycemia could also potentially provide a basis for individualized glycemic targets in patients treated with insulin in hospital." (PMID 29233143, 2017). "Although the recommended target blood glucose level (BG) is 140–180 mg/dL for critically ill patients, recent studies conducted in patients undergoing surgery showed a significant benefit of intensive insulin therapy for the management of perioperative hyperglycemia." (PMID 29863158, 2017). "During the last decades, the intensive use of insulin or other drugs, which stimulates insulin secretion, as the main treatment to prevent hyperglycemia and its long-term complications has resulted in an increase in the incidence of hypoglycemia in diabetic patients." (PMID 28115020, 2017). "Insulin requirement to regulate hyperglycemia was short-lived." (PMID 28588004, 2017). "Our findings suggested that increased mSeP chronically impairs glucose metabolism, insulin resistance and insulin secretion in KKAy mice, and that mSeP-neutralizing Ab ameliorate hyperglycaemia in KKAy mice, at least in part, by improving insulin resistance and insulin secretion." (PMID 29162828, 2017). "As T1D patients are often accompanied by insufficient insulin, strenuous exercise may also lead to hyperglycemia and ketoacidosis." (PMID 29097999, 2017). "Since STZ injection lead to hypoinsulinaemia resulting in hyperglycaemia, we next tested whether insulin injection, restoring physiological insulinaemia and glycaemia, impacts on tau hyperphosphorylation in STZ injected mice (STZ LD Ins and STZ HD Ins groups)." (PMID 28402338, 2017). "Acute hyperglycemia also inhibits cardioprotective responses, blocking ischemic pre- and post-conditioning, remote ischemic perconditioning, anesthetic pre- and post-conditioning, together with glucose-insulin-potassium (GIK) protection." (PMID 29202762, 2017).
Hyperglycemia (continued). "In humans, Broglio and colleagues found that acute administration of acyl-ghrelin in the fasted state significantly reduced plasma insulin while promoting hyperglycaemia, however, a continuous infusion stimulated insulin secretion secondary to elevated glucose levels." (PMID 28134808, 2017). "Mice with a specific deletion of the insulin signaling-related Pdk1 gene in pancreatic β cells showed a progressive decrease in pancreatic β cell mass that resulted in hypoinsulinemia and severe hyperglycemia." (PMID 28886131, 2017). "Large amounts of intravenous glucose may result in hyperglycemia, hypertriglyceridemia, and hepatic steatosis, which can, however, be prevented to a considerable extent by insulin therapy targeting normoglycemia." (PMID 29187261, 2017). "Exogenous GLP-2 decreased resection-induced hyperglycemia in an insulin-independent manner." (PMID 28738080, 2017). "Such compounds may display synergistic effects to antagonize hyperglycaemia, and hence significantly improve insulin sensitization." (PMID 28933230, 2017). "Consequently to the impairment in the capacity to secrete and produce insulin, the other characteristics follow up, such as hyperglycemia, increase in plasma fat and TG, liver inflammation, glucotoxicity and so on." (PMID 29220408, 2017). "Insulin withdrawal following chronic infusion induced transient hyperglycaemia—most likely a consequence of reduced endogenous insulin production—as well as transiently decreased food consumption and body weight and apparent increased systemic oxidative stress." (PMID 28421113, 2017). "It is well known that long-term HFD could induce hyperglycemia and elevations of blood insulin levels." (PMID 28867797, 2017). "Insulin normalized hyperglycemia, hypertension,oxidative stress, and renal injury; inhibited renal Nrf2 andangiotensinogen (Agt) gene expression; and upregulated heterogeneousnuclear ribonucleoprotein F and K (hnRNP F and hnRNPK) expression in Akita mice with T1D." (PMID 28324005, 2017). "Fifth, liraglutide usually increases insulin secretion in hyperglycemia." (PMID 28977981, 2017). "Therefore, glinides can reduce postprandial hyperglycemia and improve the first phase insulin secretion." (PMID 29089472, 2017). "Need for treatment with insulin or metformin as an indicator of severity of hyperglycemia may reflect impairment in β-cell function in women exposed to gestational diabetes." (PMID 28491872, 2017). "From these results, we can conclude that the activation of AGEs/RAGE and inflammation induced by hyperglycemia and insulin resistance may worsen the pathology of AD in this model." (PMID 28467789, 2017). "Notably, those insulin-producing duct cells have displayed some extent of glucose responsiveness ex vivo and the capacity of reversing experimental hyperglycemia in vivo." (PMID 29096722, 2017). "Thus, impairments in glucose uptake (i.e., a prediabetic state) can be chronically established due to changing the set point for glycemia, leading to further insulin insensitivity, and hyperglycemia." (PMID 29097992, 2017). "Stimulation of glucose production can lead to hyperglycaemia if the insulin response is inadequate." (PMID 28374068, 2017). "None of the dietary comparisons showed a significant association to start insulin therapy to manage hyperglycemia during pregnancy in our post-hoc NMA analysis (data not shown)." (PMID 28771519, 2017). "Considering that hyperglycemia apparently occurred in the DC group, we examined whether CO-EtOAc plays a role in the regulation of insulin signaling." (PMID 29036927, 2017). "Potentially this might lead even to hyperglycaemia and the need of following insulin therapy to overcome the inhibitory effect on insulin secretion." (PMID 28576129, 2017).
Hyperglycemia (continued). "In contrast, in the case of hyperglycemia in obese or diabetic mice, 11β-HSD1 deficiency or inhibition of 11β-HSD1 results in lower fasting glucose levels, attributed to decreased hepatic gluconeogenesis and increased insulin sensitivity." (PMID 29062028, 2017). "Use of insulin and sulfonylureas to manage hyperglycemia may additionally worsen ischemic injury, morbidity and mortality." (PMID 29202762, 2017). "Hyperglycaemia and hyperinsulinaemia delay gastric emptying and small intestinal transit in both diabetic and nondiabetic patients, whereas postprandial ghrelin levels correlate inversely with glucose and insulin levels." (PMID 28584525, 2017). "Moreover, HOMA models assume the linear insulin response to increasing glucose levels and the use of these models should be carefully considered in subjects with fasting hyperglycemia." (PMID 28575103, 2017). "which resulted in frank hyperglycaemia and a slight decrease in circulating serum insulin (85.8%)." (PMID 28129400, 2017). "The present study was designed to test the hypothesis that acute hyperglycemia diminishes the cardioprotective effects following a 20-min pre-ischemic pre-conditioning with insulin in the isolated rat heart." (PMID 28376800, 2017). "The reduction in endogenous insulin production precipitates the onset of hyperglycaemia." (PMID 28129400, 2017). "Similarly, UC-MSC infusion significantly ameliorated hyperglycemia in T2D rats and decreased inflammatory activity, which resulted in improved insulin sensitivity in insulin target tissues." (PMID 29096724, 2017). "Thus, in the PP zone, where Irs1 is less abundantly expressed and Irs2 expression is downregulated, insulin signalling is impaired despite the hyperinsulinemia, leading to the impaired suppression of gluconeogenesis and hyperglycaemia." (PMID 27708333, 2016). "In this analysis, only two variables – age and hyperglycemia frequency – were associated with the need for insulin at discharge among patients without pretransplant DM." (PMID 28031946, 2016). "We have observed that insulin delivered right at mealtimes may result in peak postprandial hyperglycemia due to mismatch of glucose absorption into the blood stream and timing of insulin delivery." (PMID 27337958, 2016). "The marked effects of the loss of a single Pdx1 allele on the progressive development of glucose intolerance and impaired glucose-stimulated insulin secretion indicate that Pdx1+/− mice may be a reasonable hyperglycemia model for analyzing AD pathogenesis." (PMID 27406855, 2016). "Disorders in insulin secretion or insulin action, or both, lead to hyperglycaemia." (PMID 27462470, 2016). "We hypothesized that long-term EPA treatment would predominantly improve postprandial state of insulin secretion and postprandial hyperglycemia and hypertriglyceridemia, and lead to prevent development of DM in patients with newly diagnosed IGM." (PMID 27565734, 2016). "In addition, the treatment with CPLE decreased hyperglycemia, increased insulin secretion in cultured pancreatic cells and preserved pancreatic β cells." (PMID 27128930, 2016). "It is also important to note that the rate of continuous nutrition also played a role in whether SQ Lispro insulin produced “rebound hyperglycemia”." (PMID 26819233, 2016). "IL-1r−/− developed hyperglycemia and lower insulin levels in response to streptozotocin (unpaired t-test; P=0.0001 and P=0.04 respectively), but in the absence of IL-1r no prolongation of QT and QTc intervals after DM induction could be observed." (PMID 27882934, 2016). "However, proinsulin measurement is unavailable to most hospital laboratories, and the proinsulin to insulin ratio will likely be altered by exogenous insulin used to treat hyperglycemia." (PMID 27504458, 2016).
Hyperglycemia (continued). "T2DM is characterized metabolically by defects in both insulin secretion and insulin action, resulting in hyperglycemia, and is histopathologically characterized by the presence of fibrillar amyloid deposits in the pancreatic islets of Langerhans (islet amyloid)." (PMID 26636105, 2016). "It was found that such increased sensitivity could result in “rebound hyperglycemia” and increased GV when the continuous nutrition was at goal, provided an ultrashort SQ insulin analog was used." (PMID 26819233, 2016). "Furthermore, F2 offspring displayed hyperglycemia at birth and increased insulin secretion from the pancreatic islets in adulthood." (PMID 26881249, 2016). "Moreover, replenishment of adipsin to diabetic animals treated hyperglycemia by boosting insulin secretion." (PMID 26909486, 2016). "Operationally, the pathophysiological presentations of prolonged hyperglycemia may be categorized within insulin-dependent and insulin-independent, type 1 and type 2 diabetic phenotypes, respectively." (PMID 27084094, 2016). "Moreover, patients with T2DM also need to maintain a high enough level of basal insulin to prevent fasting hyperglycemia." (PMID 27148163, 2016). "As previously discussed, the currently investigated pathways of DN pathogenesis mainly focus on the cellular damage associated with the various cascades activated in response to hyperglycemia, yet there is growing interest in the role of neuronal insulin signaling in DN development and progression." (PMID 28066166, 2016). "Insulin is undoubtedly the first-line treatment for preoperative and intraoperative hyperglycemia." (PMID 27656261, 2016). "Insulin replacement corrects insulin deficiency and hyperglycaemia but does not treat the underlying autoimmune T lymphocyte–mediated destruction of the insulin-producing β cells of the pancreatic islets." (PMID 27727279, 2016). "A recent study found that maternal gestational glycemia inversely correlates with a child’s insulin sensitivity and beta cell response —the implication being that intrauterine hyperglycemia programs for dysfunctional beta cell secretion as well as peripheral insulin target tissues." (PMID 27196053, 2016). "In addition, we show that short-term in vivo treatment with low dosages of two molecularly distinct proteasome inhibitors celastrol and epoxomicin reverse hyperglycemia in mice with β-cell failure by increasing insulin production and insulin sensitivity." (PMID 27110686, 2016). "Transient hyperglycemia may occur within the first six months due to acute or chronic rejection, pancreatitis, or a marked increase in insulin resistance due to weight gain." (PMID 28702248, 2016). "It is not known which metabolic factor(s) contribute to cognitive impairment; however, our previous study demonstrated that endoplasmic reticulum stress and impaired insulin signaling were only present in models of MetS with hyperglycemia/impaired glucose tolerance." (PMID 27676071, 2016). "Thus, we assume that the production of insulin to control hyperglycemia induced by such envenoming remains high and, along with a decrease in glycogenolysis (due to hepatic glycogen depletion), causes a reduction of glucose levels." (PMID 27660634, 2016). "It has been shown recently that administration of STZ to Gcgr−/− mice disrupted 90% of the beta cells and abolished glucose-induced insulin secretion yet failed to cause hyperglycaemia." (PMID 27053237, 2016). "Previous studies indicate that insulin and hyperglycemia suppress circulating ghrelin levels." (PMID 26998491, 2016). "An intraperitonealinfection of recombinant Pdx1 into streptozotocin-induced diabetic mice inducedamelioration of hyperglycemia.Ductal cells of adult mice transduced with an adenoviral vector carrying thePdx1, Pax4, Ngn3, and NeuroD genes start insulin secretion." (PMID 27795842, 2016).
Hyperglycemia (continued). "In our previous study, we have demonstrated that DNJ could alleviate hyperglycemia by improving skeletal muscle insulin sensitivity in db/db mice." (PMID 26927057, 2016). "Chronic exposure to hyperglycemia (glucotoxicity) may further impair β cell function and insulin action and contribute to the development of hyperglycemia." (PMID 27595114, 2016). "Levels of blood glucose and plasma insulin in overnight-fasted or randomly fed states were unaffected in both 12-week-old C2αD1268A/WT male and female mice, although a slight hyperglycaemia and a tendency to hyperinsulinaemia was observed in male mice under fed conditions." (PMID 27138914, 2016). "Altogether, these findings indicate that Gcgr-/- mice are not protected against hyperglycemia after near-total β-cell loss, but develop classical signs of type 1 diabetes and require insulin therapy." (PMID 27092792, 2016). "Treatment with insulin may improve hyperglycemia, but it cannot protect the body from chronic exposure to high glucose levels." (PMID 27340675, 2016). "During dexamethasone treatment hyperglycaemia requiring insulin was reported in 17 episodes (13%)." (PMID 27845429, 2016). "In the Cyp1a1mRen2 rat, after 28 weeks of hyperglycaemia and hypertension, a reduction in albuminuria was observed following optimization of glycemic control by implanting insulin pellets subcutaneously and normalizing blood pressure through removal of indole-3-carbinol from the diet." (PMID 26814757, 2016). "The enzyme glucokinase controls insulin release from the beta cell by sensing the ambient glucose concentration; inactivation of this enzyme renders the beta cell less capable of responding to hyperglycemia." (PMID 28702252, 2016). "In such cases, treatment of maternal hyperglycemia with insulin is warranted." (PMID 28702252, 2016). "Whereas miR-133a induction mediated the hyperglycemia-induced repression of insulin biosynthesis and could therefore be involved in β-cell differentiation, miR-34a and miR-146 are probably implicated in β-cell survival." (PMID 28123396, 2016). "In contrast, hyperglycemia and decrease in insulin level were found in CPF3.5 rats." (PMID 27760213, 2016). "The anti-hyperglycemia therapy includes insulin therapy and oral hypoglycemic agents." (PMID 27142369, 2016). "In an insulin tolerance test, injection of hyperglycemic cKO mice led to an eventual drop of glucose levels down to those seen in WT, but immediate reversal back to hyperglycaemia." (PMID 27464507, 2016). "Thus, at 20 week of HFD, cKO were still transiently responsive to exogenously provided insulin, but endogenous elevated levels of insulin were insufficient to counteract hyperglycaemia." (PMID 27464507, 2016). "Hyperglycemia and reduction of plasma insulin have been attributed to abnormal islet function." (PMID 27079523, 2016). "Higher levels of C-peptide in vivo after glucose challenge and control of hyperglycaemia in STZ-treated mice strongly suggest that insulin-producing cells derived from the interactions between EBs and ECs maintain their functional capacity after transplantation in SCID mice." (PMID 27567623, 2016). "As a metabolic disease, T2DM is characterized by insulin secreted from pancreatic β cells that cannot meet the demands of insulin sensitivity or insulin resistance, which might result from over-nutrition with chronic hyperglycaemia and hyperlipidaemia." (PMID 27349479, 2016). "Insulin increases glucose utilization and reduces the damage of hyperglycemia to brain cells." (PMID 27626493, 2016). "Insulin has traditionally been the focus of attention for diabetic research, but in recent years glucagon has received increased attention, as hyperglucagonemia contributes to the hyperglycemia present in T2D." (PMID 27136422, 2016). "In addition to these reports, studies have shown that chronic hyperglycemia impairs islet allograft insulin secretion and that this defect is exacerbated when the β-cell mass is reduced." (PMID 27872862, 2016).